INS (insulin)
Diseases named in the same sentence as INS in open-access papers (continued):
Sharing a sentence is not in itself a finding about the gene and the disease.
diabetes (continued). "Predictors of diabetes among women with a history of GDM include maternal antepartum and early postpartum glycemia, insulin use during pregnancy, pancreatic β-cell compensation for higher insulin resistance and GDM recurrence and family history of diabetes, especially having a mother with diabetes." (PMID 22196129, 2011). "Results showed that salidroside possessed hypoglycemic activity and protective effects against diabetes-induced oxidative stress, which could significantly reduce FBG, TC, TG and MDA levels, and at same time increase serum insulin levels, SOD, GPx and CAT activities." (PMID 22134398, 2011). "Drug discovery efforts that target diabetes-related molecular alterations that are not normalized by insulin are needed to develop an adjuvant therapy that, in conjunction with insulin replacement, restores retinal gene expression and tissue function to a healthy state." (PMID 21575160, 2011). "Our data suggest that this response might reflect a state of insulin resistance; however our insulin tolerance tests do not support this insulin-resistant component in diabetes progressors." (PMID 22046124, 2011). "Undoubtedly, the presence of cognitive impairment in diabetes may have significant impact on the day to day management of these patients; not least in the area of insulin and drug administration." (PMID 22162800, 2011). "We have already characterized a small number of insulin therapy resistant changes in retinal protein expression with diabetes and these transcriptomic findings suggest that the quantitative proteomic analysis of retinal protein expression not normalized by insulin treatment is warranted." (PMID 21575160, 2011). "Interestingly, both insulin-independent normalization of systemic hyperglycemia and ocular delivery of insulin without normalization of blood glucose partially reversed diabetes-induced retinal cell death." (PMID 22046295, 2011). "DM (Diabetes mellitus) is a metabolic disorder characterized by chronic hyperglycemia or increased blood glucose levels with disturbances in carbohydrate, fat and protein metabolism resulting from absolute or relative lack of insulin secretion." (PMID 21251279, 2011). "Fasting plasma insulin (~25 pmol/L), glucose (~13 mmol/L) and triglyceride (~0.5 mmol/L) concentrations and a positive energy balance (body weight gain of ~1.5 kg/week) without the occurrence of ketosis indicated a mild form of diabetes in the pigs." (PMID 21756316, 2011). "Similarly, data from the British Women's Health and Heart Study revealed associations between GGT and GPT with fasting glucose, fasting insulin and HbA1c as measures of glucose homeostasis in 3086 without and 308 women with diabetes." (PMID 21850244, 2011). "When liver is insulin resistant, insulin no longer suppresses gluconeogenesis, but still stimulates lipogenesis, creating a vicious cycle that aggravates insulin resistance and ultimately contributes to the onset of overt diabetes." (PMID 21731709, 2011). "For people with diabetes who do not use insulin, personalized structured education may be the missing link to deriving benefits from SMBG." (PMID 21979293, 2011). "We have further measured blood inflammatory biomarkers, free fatty acids, insulin, adiponectin, lipid profiles, liver oxidative stress biomarkers, as well as DPP-4 and PTP-1B activities, aiming to better understand the mechanisms by which BBR improves glucose metabolism and homeostasis in diabetes." (PMID 22363882, 2011). "The higher proportions of patients that used insulin in the control group could not be explained by the longer duration of diabetes or age." (PMID 21600064, 2011). "A single mealtime insulin claim may indicate a response to an acute hyperglycemic event and not represent a true intensification of diabetes management." (PMID 21226935, 2011).
diabetes (continued). "Rescued, Partially Rescued, and Not Rescued are those gene expression changes which are manifest after one month of diabetes, before initiation of insulin treatment, and are normalized, partially normalized, or not normalized with chronic insulin treatment, respectively." (PMID 21575160, 2011). "Diabetes mellitus (DM) is considered to be a syndrome associated with disorders in the metabolism of carbohydrates, lipids, and proteins caused by the absolute or relative lack of insulin, and it affects approximately 3 to 10% of the women in the gestational phase." (PMID 21647314, 2011). "More specifically we looked at whether diabetes adversely affects retinal neurons due to lack of neurotrophic levels, such as in the case of insulin, PEDF, and BDNF, and/or due to lack of activity, such as in the case of VEGF and NGF." (PMID 21293735, 2011). "By comparing MetS (pre-diabetic) and diabetic patients with control patients without these conditions, we examined the effects of the insulin-resistant state before diabetes (and anti-diabetes medication) commenced, and the effects of diabetes before heart failure developed." (PMID 21929744, 2011). "The Not Prevented phenotype genes were expressed at non-diabetic control levels at one month of diabetes, but became significantly dysregulated with a longer duration (three months) of diabetes regardless of insulin treatment for the last one and a half months." (PMID 21575160, 2011). "This analysis strongly demonstrated that local insulin signaling but not hyperglycemia was crucial in controlling several aspects of the immune response to diabetes, including the classical complement pathway, cytokine-induced signaling pathways and lipid metabolism in the retina." (PMID 22046295, 2011). "It is somewhat surprising that education is conspicuously underrepresented, even though clinical guidelines suggest it belongs in class A. Structured and personalized education and actionable feedback are widely suggested as the missing link for people with diabetes who do not use insulin." (PMID 21979293, 2011). "Based on the results of the present study in obese individuals with T2DM and other studies in lean to obese subjects without diabetes, it transpires that the onset of action of the rapid-acting insulin analogues is not delayed in obese subjects when using a specific injection site." (PMID 21205115, 2011). "First, the published data do not allow differentiating type 1 from type 2 diabetes or insulin-treated from non-insulin-treated diabetes, and it might be possible that there are differences in outcomes between these groups." (PMID 21914173, 2011). "The insulin-loaded microemulsion containing 10% oleic acid, 38% aqueous phase, and 50% surfactant phase with 2% DMSO as permeation enhancer showed maximum permeation flux and can be transdermally administered in the treatment of insulin-dependent diabetes mellitus with improved patient compliance." (PMID 22389858, 2011). "In addition, glulisine was shown to have a faster onset of action in obese subjects without diabetes and faster absorption with higher postprandial insulin levels in people with T2DM compared with lispro." (PMID 21205115, 2011). "In 1993, a report from American Diabetes Academy and the diabetes control and complications trial(DCCT)published in the New England Medical Journal verified that intensification therapy of insulin could keep the blood glucose at normal level and postpone the occurrence and the development of DN." (PMID 20804623, 2010). "Notably, a proportion of our subjects probably had unidentified diabetes or IGT, and the increase in proinsulin/insulin with age observed in this study could conceivably just reflect the increase in individuals with abnormal glucose tolerance." (PMID 21162746, 2010). "If not carefully controlled, insulin and glucose potentially could affect aqueous flow and mask or mute effects due to the diabetes." (PMID 20573241, 2010).
diabetes (continued). "This long-lasting (one year) islet-protecting effect, which arrests diabetes progression without the need for insulin therapy, appears to involve the precipitous reduction of autoreactive lymphocytes through enhancement of activation-induced cell death of T and B lymphocytes." (PMID 20949090, 2010). "Generally, in contrast with patients affected with other forms of diabetes, treatment with insulin should not target a very tight control of blood glucose, in order to avoid hypoglycemia, which may trigger episodes of acute aggravation of the disease." (PMID 21050479, 2010). "We have shown in the current study that dietary leucine supplementation significantly improves glucose-insulin homeostasis in two etiologically distinct mouse models of obesity/diabetes, RCS10 and Ay, even though the treatment has no long term effect on energy balance in these mouse models." (PMID 20624298, 2010). "Although functional analyses showed that the mutant channel was highly sensitive to sulfonylureas, there was no clinical effect on metabolic control or insulin requirement after four weeks of glibenclamide treatment (1.0-1.2 mg/kg/24h) 8 years after diagnosis of diabetes." (PMID 20863361, 2010). "The reason of the difference may come from the diabetes/IFG group including only early stage diabetes patients untreated with antidiabetic agents but not moderate to severe diabetes patients treated with oral antidiabetic agents and/or insulin." (PMID 20470376, 2010). "In type 2 diabetes mellitus whose pathogenesis is tightly linked to increased body mass index, it has been shown that the insulin sensitivity is decreased suggesting a direct negative relationship between VEGF concentrations and insulin sensitivity." (PMID 20830305, 2010). "Our findings indicate that a positive family history of diabetes may play a role, not related to the classical T1 D loci (HLA and INS-VNTR)." (PMID 20863361, 2010). "Blood sugar control fails in people with diabetes because they make no insulin (type 1 diabetes) or, more commonly, because the fat and muscle cells that usually respond to insulin by removing excess sugar from the blood have become insulin insensitive (type 2 diabetes)." (PMID 20186272, 2010). "The diabetes was treated with oral medication in 47% of patients; 29% of patients were treated with insulin, 14% of patients were treated with combined oral and insulin therapies, and 11% of patients did not receive either oral or insulin treatment." (PMID 21050469, 2010). "Significantly, our results reveal that insulin signaling is normally regulated by IDE activity not only extracellularly but also within cells, supporting the longstanding view that IDE inhibitors could hold therapeutic value for the treatment of diabetes." (PMID 20498699, 2010). "For this substudy, patients were classified according to whether or not they had a known diagnosis of insulin-treated diabetes mellitus." (PMID 20132545, 2010). "In conjunction with the availability of mice expressing GFP under the insulin promoter in both B6 and NOD background and strains expressing red or far-red fluorophores controlled by a variety of promoters, we believe there is ample opportunity to translate our approach to other diabetes models." (PMID 21203413, 2010). "In patients on an oral regimen at baseline, there was a remarkable improvement of diabetes-related distress regardless of whether those patients remained on an oral regimen or were switched to insulin treatment." (PMID 20920319, 2010). "Diabetes mellitus, often simply referred to as diabetes, is a condition with elevated blood glucose levels, as a result of either the body not producing enough insulin, or because cells do not properly respond to the insulin that is produced." (PMID 20877687, 2010). "Going without insulin from time to time was nothing unusual to Helen which proved her difficult situation in spite of our impression of Helen as one of the more resourceful patients at the diabetes clinics." (PMID 20441575, 2010).
diabetes (continued). "Patients' negative attitudes towards starting insulin therapy are based on their beliefs that the need for insulin therapy indicates a greater severity of the disease and proves their failure to self-manage the diabetes adequately." (PMID 20920319, 2010). "This increased glycaemia may represent the first step towards manifest diabetes as a consequence of primarily β-cell dysfunction with or without simultaneous increasing insulin resistance." (PMID 20529356, 2010). "Whether drinking a simple cup of tea out of the leaves or taking extracts of the neem leaf, neem significantly and consistently reduced insulin requirements for nonkeytonic, insulin fast, and insulin sensitive forms of Diabetes." (PMID 27956991, 2010). "Although our functional analyses showed that the channel was highly sensitive to sulphonylureas, our patient (8 years after diagnosis of diabetes) did not benefit from glibenclamide after 4 weeks of treatment (1.0-1.2 mg/kg/24h) in terms of metabolic control and insulin requirement." (PMID 20863361, 2010). "Diabetes is not always associated with elevated IOP, but if it is found, it could be explained in part by higher insulin resistance and chronic hyperglycemia." (PMID 20573241, 2010). "In addition, we compared patients with a history of insulin-treated diabetes to a cohort consisting of non-diabetics and non-insulin-treated diabetics, and have no data on the numbers of non-insulin-treated diabetics in this cohort." (PMID 20132545, 2010). "The risk was observed for patients with longer and shorter durations of diabetes, regardless of whether measured as time since diagnosis or time since starting insulin." (PMID 19997624, 2009). "Insulin therapy is beneficial, not deleterious, in the management of diabetes." (PMID 19573240, 2009). "Blood-sugar control fails in people with diabetes because they make no insulin (type 1 diabetes) or because the fat cells and muscle cells that usually respond to insulin by removing sugar from the blood have become insulin insensitive (type 2 diabetes)." (PMID 19787025, 2009). "The reduction innutrients appears to inhibit the insulin and nutrient-sensing target ofrapamycin (TOR) protein signaling pathway, whereas obesity activates it,elevating diseases that accompany the metabolic syndrome, such as diabetes, atherosclerosisand dementia." (PMID 20157573, 2009). "In several studies in subjects with diabetes, GLP-1- whether administered by intravenous or subcutaneous infusion – normalized both fasting and postprandial glycemia by enhancing glucose-mediated insulin secretion, as well as by suppressing glucagon secretion." (PMID 19619327, 2009). "In the non-I/R heart, diabetes significantly reduced the level of phosphorylated Akt (P-Thr 308-Akt and P-Ser 473-Akt) protein compared to age-matched controls, while treatment of insulin yielded a higher phosphorylated Akt (P-Thr 308-Akt) level in comparison to the diabetic group." (PMID 19706162, 2009). "Basal insulin therapy, with or without OADs, can be an effective treatment option with just one daily injection and this simple regimen allows patients to adjust to a major change in the management of their diabetes." (PMID 19504715, 2009). "Therefore, the results of this study seem to indicate that sorbitol accumulation is most likely not related to skeletal muscle dysfunction in insulin-treated diabetes." (PMID 20016800, 2009). "The IN CONTROL-trial is designed to explore whether feedback from self-monitoring of glucose in T2DM patients who do not require insulin can affect diabetes specific emotional distress and increase self-efficacy." (PMID 19397795, 2009). "By analyzing the BMI through the insulin dose prior to the transplant, it was observed that the BMI greater than 28 kg/m2 and daily insulin dose greater than 70 U, regardless of the diabetes type (1 or 2), were the ones that had hyperglycemia in 80 to 90% of the times." (PMID 19825194, 2009).
diabetes (continued). "Approximately 10% of diabetes patients have type 1 diabetes mellitus, an autoimmune disease that destroys insulin-producing beta cells in the pancreas leading to a decrease in the concentration of insulin in the body, and the remainder have type 2 (non-insulin-dependent diabetes mellitus)." (PMID 20523870, 2009). "Because diabetes is a metabolic disorder which is characterizedas complete or partial lack of insulin functionality, therapies can be done by makingup for the lack of insulin supply by exogenous insulin replacement." (PMID 18566688, 2008). "Morbidity, mortality, and quality of life for people living with diabetes in low- or middle-income countries may decline further if insulin and appropriate health care is neither available nor accessible." (PMID 18284685, 2008). "When insulin secretion is not sufficientand elevated glucose levels prevail,diabetes becomes overt." (PMID 18604303, 2008). "Additional trials are currently ongoing [such as the Finnish Diabetes Prediction and Prevention Project (DIPP)] or planned [Primary Oral/intranasal INsulin Trial (Pre-POINT)] and aim to determine the efficacy of nasal insulin as well as the optimum insulin dose." (PMID 19046214, 2008). "The more prevalent form of diabetes is type-2 (noninsulin dependent DM), a condition which often develops over a period of time, involves reduced responsiveness of tissues to circulating insulin, and is often controlled by diet or oral hypoglycemic agents." (PMID 20142943, 2008). "Insulin-treated patients have been found to have significantly greater treatment satisfaction than non-insulin treated patients with diabetes, though this significant difference was also lost after adjustments were made for age, gender, body mass index and duration of diabetes." (PMID 17286868, 2007). "Eligibility criteria for this randomized placebo controlled trial included: age 30–80, HbA1c ≤ 10%, diabetes therapeutic regimen consisting of diet or no more than two hypoglycemic agents or insulin with or without one additional oral agent (usual diabetes therapy; UDT)." (PMID 17592632, 2007). "However, in diabetes patients there is a lack of natural insulin and so manufactured insulin has to be given by injection after blood sugar testing." (PMID 17326710, 2007). "In people with type II diabetes and people without diabetes, insulin resistance is compensated by increased insulin secretion by the β-cells, whereas in type I diabetes, insulin resistance may be present but β-cell function remains negligible." (PMID 17224924, 2007). "In contrast, duration of hypoglycaemia is usually much longer than predicted based on the commonly accepted kinetics of insulin absorption and action, whereas the degree of hypoglycaemia may not be so profound, especially in patients who have diabetes." (PMID 17963523, 2007). "Moreover, people without diabetes are more likely than diabetic patients to develop recurrent hypoglycaemia, in relation to the lack of insulin antibodies, insulin resistance and endogenous insulin secretion, in response to glucose infusion." (PMID 17963523, 2007). "Persons with diabetes who perceive injecting insulin as burdensome may experience more negative health outcomes, whereas patients who are satisfied with their treatments are more likely to maintain positive physical and psychological health." (PMID 17286868, 2007). "However, as already observed in previous work, it is interesting to note that patients, regardless of their type of diabetes and insulin therapy, would be very much in favour of inhaled insulin if this were available." (PMID 17727695, 2007). "Hence, it is not possible for patients with diabetes to modify insulin secretion naturally in response to a change in glucose levels, and so blood glucose levels can rise and fall beyond healthy levels." (PMID 17326710, 2007).